CRP (C-reactive protein)
Diseases named in the same sentence as CRP in open-access papers (continued):
Sharing a sentence is not in itself a finding about the gene and the disease.
appendicitis (continued). "However, complicated appendicitis can still occur in patients with normal WBC and CRP levels, reinforcing the importance of imaging-based assessment." (PMID 40158350, 2025). "Serum CRP is a sensitive, non-specific biomarker for inflammation and is broadly used in clinical diagnosis of infectious diseases, including appendicitis." (PMID 40871545, 2025). "Despite the clinical suspicion of appendicitis, laboratory findings, including normal CRP and borderline low WBC, did not support significant systemic inflammation, complicating the preoperative diagnosis." (PMID 41209983, 2025). "Conventional biomarkers such as LC and NC significantly increase with the severity of acute appendicitis, diverticulitis, and cholecystitis, except pancreatitis, whereas CRP did not significantly increase in complicated diverticulitis or pancreatitis." (PMID 40067493, 2025). "The false negative rate was similar to results from CRP serum levels, with 4 of 46 children (8.7%) with confirmed acute appendicitis incorrectly identified as negative." (PMID 40871545, 2025). "CRP levels were significantly higher in the gangrenous appendicitis group (141.90 ± 147.86 mg/L) compared to the non-gangrenous appendicitis group (41.49 ± 53.67 mg/L) (p < 0.001)." (PMID 40572758, 2025). "Conversely, patients with CRP <100 mg/l at 24 h of antibiotic treatment for uncomplicated acute appendicitis have a 99% likelihood of successful non-operative primary management." (PMID 40741675, 2025). "The probability that an individual who does not have positive CRP/MAS did not have acute appendicitis." (PMID 39677268, 2024). "This disparity indicates that the correlation between CRP and LOS could potentially be influenced by factors such as peritonitis, drainage tube placement, and the specific pathologic characteristics of appendicitis." (PMID 39726534, 2024). "However, little research has examined the relationship between CRP levels and length of stay (LOS) in children diagnosed with appendicitis." (PMID 39726534, 2024). "Past research has demonstrated that CRP serves as a non-specific marker of inflammation, with increased plasma CRP levels indicating infection and aiding in the clinical assessment of appendicitis." (PMID 39726534, 2024). "It introduces C-reactive protein (CRP) into the score and is able to predict acute appendicitis with higher specificity, decreasing the rate of negative appendicectomy." (PMID 37514986, 2023). "Several markers with different sensitivity and specificity rates, e.g., including C-reactive protein (CRP), mean platelet volume (MPV), white blood cell (WBC) count, ESR and red cell distribution width (RDW), etc., have been explored for the diagnosis of acute appendicitis." (PMID 37685553, 2023). "Although bilirubin is more specific to appendicitis, WCC and CRP levels are more sensitive." (PMID 37929270, 2023). "There were significant differences between patients with and patients without complicated appendicitis in most characteristics measured including age, gender, neutrophil, C-reactive protein, diameter of appendix, and appendix position." (PMID 37090195, 2023). "In our study, hyperbilirubinemia yielded a PPV of 95.92%, while CRP exhibited a specificity of 60% for non-perforated appendicitis." (PMID 37929270, 2023). "To determine the effect of the ERAS perioperative regimen on postoperative inflammatory status in patients with appendicitis, we measured WBC, CRP, PCT, and IL-6 levels in patients with appendicitis before surgery, 6 h after surgery, and on the third day after surgery." (PMID 37928355, 2023). "Our research indicates that parallel assaying of the level of CRP, NGAL and IL-6 increases the probability of diagnosing of appendicitis in paediatric patients presenting at an emergency department with clinical symptoms which suggest the presence of this disease." (PMID 37509519, 2023).
appendicitis (continued). "We validated the diagnostic performance of 8 existing scoring systems and proposed a new scoring system to predict complicated appendicitis without the need for serum C-reactive protein." (PMID 37973644, 2023). "Our study demonstrated that WBC count, CRP level, ESR, temperature, and ascites were clinical factors that could differentiate complicated appendicitis in the decision tree model." (PMID 36900066, 2023). "Additionally, the NPV of CRP is higher than WBC, which makes it a better test compared to WBC in ruling out appendicitis." (PMID 37873039, 2023). "Notably, participants agreed on the need to request CRP-POCT (78%), commenting that CRP is widely used when managing suspected appendicitis in children." (PMID 37872491, 2023). "This was detected in a prior report in which it was found that TLC, ESR and CRP in children with acute appendicitis are significantly higher as compared to those who have nonspecific abdominal pain." (PMID 37862106, 2023). "In the literature, there is no consensus on the use of CRP in the diagnosis of acute appendicitis, but it has been emphasized that CRP can be helpful in the diagnosis of advanced and complicated appendicitis." (PMID 36225527, 2022). "The mean and standard deviation (SD) of white cell count (WCC), neutrophil-to-lymphocyte (NLR) ratio, platelet-to-lymphocyte (PLR) ratio, and c-reactive protein (CRP) levels in patients with histologically normal, uncomplicated appendicitis, and complicated appendicitis." (PMID 36185898, 2022). "For patients after surgery, CRP can help distinguish acute appendicitis from other noninfectious abdominal pain and predict infection complications after colorectal surgery." (PMID 35991149, 2022). "Applying results to a hypothetical cohort(1000 children with appendicitis symptoms, of whom 400 have appendicitis) 60 and 40 children would be wrongly discharged based solely on WCC and ANC, respectively, 12 with combination of WCC or CRP." (PMID 36328382, 2022). "The median CRP value was higher in children with than without appendicitis at 42 mg/L (IQR: 18–83) and 5 (IQR:2 − 8 mg/L, respectively." (PMID 35535699, 2022). "The accuracy of white blood cells (WBC) and neutrophils for diagnosis of appendicitis differ among articles, as normal leukocyte counts do not exclude appendicitis, and CRP is a sensitive test, but non-specific for acute appendicitis." (PMID 36676645, 2022). "Based on the SNAPSHOT appendicitis data, patients presenting at night were younger, vomited more often, had lower CRP levels, higher leucocytes and were often not operated on within eight hours after presentation." (PMID 35453836, 2022). "They concluded TLC being more useful in predicting acute appendicitis at histology than CRP, with TLC having a sensitivity of 25%, specificity of 94% and positive predictive value of 88%, while CRP yielded a sensitivity of 52%, specificity of 91 and positive predictive value of 91%." (PMID 35495380, 2022). "Furthermore, CRP was a better marker than neutrophils and TLC in predicting both perforated and complicated appendicitis." (PMID 35495380, 2022). "We included children aged 4–18 years, with no history of appendicitis, presenting with acute abdominal pain, and having a CRP test." (PMID 35535699, 2022). "Anyway, CRP and WBC values can be normal in 8% of children with proven appendicitis." (PMID 36676645, 2022). "The differences in the white blood count (p = 0,221) and CRP serum levels (p = 0,283) in our patients with appendicitis treated in the year 2019 vs 2020 were nonsignificant." (PMID 34907247, 2021). "Although there is no specific laboratory marker for the diagnosis of appendicitis, various parameters, such as white blood cell (WBC) count, C-reactive protein (CRP), neutrophil-lymphocyte ratio (NLR), and platelet-lymphocyte ratio (PLR) are used to diagnose acute appendicitis." (PMID 34646676, 2021).
appendicitis (continued). "In comparison to Interleukin-6 (IL-6) and CRP, no other biomarkers have been proven effective in diagnosing appendicitis." (PMID 34064691, 2021). "However, the appendicitis inflammatory response (AIR) score, which incorporates C-reactive protein (CRP) and gradation of RLQ pain, was proven to outperform the Alvarado score in several studies." (PMID 34501478, 2021). "Only 3 patients with acute appendicitis showed repeatedly normal WBC and CRP levels." (PMID 33907858, 2021). "If a child initially presents with abdominal pain and symptoms mimicking gastroenteritis, accompanied with RLQ pain, an absence of stool OB, and higher WBC count and CRP level, a diagnosis of acute appendicitis would be more accurate." (PMID 33050667, 2020). "In summary, patients with appendicitis were older and had peritonitis, higher preoperative WBC count or CRP level, longer time from diagnosis to surgery, appendicolith, and complicated appendicitis, which might predict a prolonged hospital stay." (PMID 33296384, 2020). "WBC, CRP, neutrophils, and urine ketones were considerably elevated in most, but not all children with appendicitis." (PMID 33313029, 2020). "We found that C-reactive protein (CRP) and lymphocyte CRP ratio (LCR) were not useful in predicting acute appendicitis." (PMID 32069909, 2020). "The results showed no patients with both WCC and CRP within the normal range had acute appendicitis, giving sensitivity and a negative predictive value of 100%." (PMID 32983436, 2020). "CT scans should be considered in children with high clinical suspicion of acute appendicitis if they have vomiting, high WBC count and elevated serum CRP concentration, despite negative or non-diagnostic US results." (PMID 32899032, 2020). "The conclusion was: no WCC count or CRP level can safely and sufficiently confirm or exclude the suspected diagnosis of acute appendicitis in patients who present with abdominal pain of 5 days or less in duration." (PMID 32983436, 2020). "So the conclusion was: patients experiencing lower abdominal pain, with normal WCC and CRP values, are unlikely to have acute appendicitis and can be safely sent home." (PMID 32983436, 2020). "Also, in 2001 JM Grönroos conducted what was seems to be a case-control study which included 200 paediatric patients with suspected acute appendicitis and reported a 7% incidence of normal WCC and CRP among patients with AA." (PMID 32983436, 2020). "As neutrophils and NETs are directly affected by intestinal inflammation, one might assume that the neutrophil-associated biomarker might be superior to current markers like CRP or WBC in predicting and differentiating appendicitis." (PMID 33106536, 2020). "Given the abdominal pain and abscess at initial presentation, as well as pain extending to the back, fever, and increased CRP, appendicitis was not inappropriate to include on the differential." (PMID 31770708, 2019). "Overall, 17 patients (5.7%) had acute appendicitis with a normal WBC and CRP." (PMID 31856705, 2019). "Acute appendicitis in patients with healthy WBC and CRP values is possible, albeit rare." (PMID 31183274, 2019). "The distribution of analyzed values for whole blood cell counts, CRP and appendiceal diameter differed between patients with and without appendicitis and between patients with complicated and uncomplicated inflammation, respectively." (PMID 31553729, 2019). "Many studies have evaluated the importance of CRP, leukocyte, and neutrophil count and percentage for the diagnosis of acute appendicitis; these studies show that none of these completely exclude the diagnosis of acute appendicitis." (PMID 31183274, 2019). "Only two out of the 6 biomarkers were included in the more in-depth analysis (CRP and PCT) while the role of the other 4 (Ferritin, SAA, RANTES, and MIG) in the progression of appendicitis may be more unclear." (PMID 30918467, 2019).
appendicitis (continued). "Using the WBC and CRP combination in the differentiation of patients with and without acute appendicitis produced high sensitivity values, and adding the NC to this combination did not lead to an increase in sensitivity." (PMID 31183274, 2019). "Literature data even clearly demonstrates that CRP is not a good tool for helping the surgeon make the diagnosis of appendicitis and it should not be measured in suspected appendicitis, thus supporting our results." (PMID 30429680, 2018). "Amongst all the laboratory tests, serum bilirubin was found to have better sensitivity and negative predictive values than WBC counts and CRP in diagnosing acute appendicitis." (PMID 29552432, 2018). "The analysis of WBC counts (except differential counts), CRP, and serum bilirubin levels and their role as predictors in complicated appendicitis were not significant." (PMID 29552432, 2018). "For perforated appendicitis, the authors concluded that changes in CRP values was not helpful for the diagnosis." (PMID 29793425, 2018). "We demonstrated that both CRP markers were not of significant utility either alone or in combination to MAS in the diagnosis of appendicitis." (PMID 29793425, 2018). "CRP negativity was also not useful to rule out appendicitis in patients with RIF pain as the NPV was only 42%." (PMID 29552432, 2018). "Our study result is similar to that of a previous study, which reported that early CRP levels were not different between a normal appendix and acute appendicitis but were significantly different between simple appendicitis and perforated appendicitis." (PMID 28747992, 2017). "Concerning CRP, it has no value in predicting acute appendicitis, but it is the most reliable biochemical marker in predicting the complications in this study result." (PMID 28747992, 2017). "Further, the necessary clinical information and routine blood tests, to combine PAS and CRP with US, are often a part of the basic workup in children with suspected appendicitis and hence do not require any special resources." (PMID 28044133, 2016). "Still, in making a diagnosis of appendicitis, many novel markers as procalcitonin have been used whose diagnostic superiority over WBC and CRP has not been demonstrated so far." (PMID 27274988, 2016). "However, it has been reported that CRP used solely or in combination with WBC is effective in the discrimination between acute and complicated appendicitis." (PMID 27274988, 2016). "If WBC and CRP values are within normal limits, even though diagnosis of AA can not be ruled out, diagnosis of complicated appendicitis is a very remote possibility." (PMID 27274988, 2016). "Among patients with PAS 4–6 and a negative US, 7% had appendicitis, and among patients with a negative US and CRP < 15 mg/L, 5% had appendicitis." (PMID 28044133, 2016). "This study showed a complicated appendicitis can be predicted by a combination of clinical variables, the number of involved segments of RPS, the maximal diameter of the appendix on CT examination, existence of appendicolithiasis, and the CRP levels." (PMID 25587352, 2014). "The negative predictive values of white cell count and C-reactive protein for acute appendicitis were 28% and 50%, respectively." (PMID 24533851, 2014). "The aim of the study is to analyze the role of C-reactive protein (CRP), white blood count (WBC) and Neutrophil percentage (NP) in improving the accuracy of diagnosis of acute appendicitis and to compare it with the intraoperative assessment and histopathology findings." (PMID 22866907, 2012). "According to Shakhatreh (2000), CRP measurement is very useful in the diagnosis of acute appendicitis, but it does not replace the clinical judgment of a surgeon." (PMID 22866907, 2012). "A study on 200 children showed that unlike the adult, normal leukocyte and CRP does not rule out acute appendicitis in pediatric cases." (PMID 22866907, 2012).
appendicitis (continued). "Diagnosing appendicitis requires long experience and clinical skills beyond the level of a newly graduated ED doctor and the diagnose is not dependent on the CRP result alone." (PMID 21906396, 2011). "In the diagnosis for appendicitis, not for surgical indication, a common blood analysis including white blood cell counts, neutrophil percentage and serum level of CRP has been demonstrated to be important." (PMID 19878592, 2009). "Numerous previous studies have shown that the CRP level enhances the precision of diagnosis of acute appendicitis, but not surgical indication." (PMID 19878592, 2009). "In our study, the CRP level did not effectively predict the diagnosis of phlegmonous appendicitis, but it predicted well the patients with advanced or perforated appendicitis." (PMID 17132173, 2006). "In a study of Paajanen appendicitis was ruled out in over 90 % of cases if both leucocytes and CRP were negative." (PMID 17132173, 2006). "Plasma CRP was significantly higher in patients with perforated appendicitis, but not in the other groups." (PMID 16759345, 2006). "However, this study did not specifically address CRP levels in patients with Campylobacter pseudo-appendicitis." (PMID 40901534, 2025). "Within Group D, the pattern was predominantly gastrointestinal (diverticulitis/appendicitis) with smaller numbers of renal non-urolithic, tumor and other entities; this is consistent with CRP tracking inflammatory pathology, while neoplastic/other categories show greater heterogeneity in CRP." (PMID 41204018, 2025). "For this reason, the Canadian Association of Paediatric Surgeons has issued a “Picking Carefully” proclamation advising against regularly obtaining CRP levels in children with suspected appendicitis, as this is considered unnecessary and does not influence the physician’s diagnosis." (PMID 41153524, 2025). "Finally, C-reactive protein is not mandatory for diagnosing appendicitis, but it is relevant to determining the severity of different inflammatory conditions, being an accessible biomarker." (PMID 39996695, 2025). "CRP serves as an indicator of advanced appendicitis rather than an early diagnosis of simple appendicitis, and of advanced inflammation as opposed to explicit appendicitis." (PMID 41153524, 2025). "This is added to the fact that other causes of RLQ abdominal pain may also present with elevated CRP levels, and therefore, CRP alone is not sufficient for diagnosing AA or complicated appendicitis." (PMID 40171038, 2025). "Despite the fact that there is some evidence that CRP may be elevated in appendicitis, the current test qualities are not high enough to be used as an independent diagnostic test." (PMID 41153524, 2025). "Of course, CRP is not an explicit indication of acute appendicitis, but the combination of increased CRP and abdominal pain in patients with hematologic malignancies or leukopenia should make one think of the possibility of an acute abdominal infection or even appendicitis." (PMID 40596935, 2025). "Unlike appendicitis and diverticulitis, epiploic appendagitis typically does not result in fever or elevated levels of white blood cells, erythrocyte sedimentation rate, or C-reactive protein." (PMID 39188448, 2024). "Nonetheless, as we observed a lot of similarity to AIR score cutoffs (around 10 mg/dL for CRP, 10 × 109/L for WBC count, and 80% for Neutrophils), the AIR score might be useful in settings where one needs a quick approximation of appendicitis or when only basic computational devices are available." (PMID 38834671, 2024). "Likewise, CRP functions as a non-specific indicator of inflammation, with elevated levels in plasma indicating infection and aiding in the clinical diagnosis of appendicitis." (PMID 39735250, 2024). "CRP levels may also provide benefits by ruling out people who do not have appendicitis, particularly when laboratory values are low 12 hours after the onset of symptoms." (PMID 39677268, 2024).